BRCA1 (BRCA1 DNA repair associated)
Diseases named in the same sentence as BRCA1 in open-access papers (continued):
Sharing a sentence is not in itself a finding about the gene and the disease.
cancer (continued). "BRCA1 deficiency blocks mitophagy, leading to the accumulation of damaged mitochondria and inflammation which is involved in tumorigenesis and cancer metastasis." (PMID 32195105, 2020). "Cancers with DNA repair defects, such as those with a BRCA1 or BRCA2 (BRCA1/2) mutation, can be treated with PARP inhibitors, which render them deficient in homologous recombination repair." (PMID 33051529, 2020). "SBS3, ID6 and ID8 signatures were significantly enriched more than other types of mutation signatures in BRCA1/2-mutated cancers expressing wild-type POLQ." (PMID 32885167, 2020). "In this study, we benchmarked the classification of BRCA1/2 variants from patients with HBOC-related cancer using MH BRCA, a novel computational technology that combines the ACMG guidelines with expert-curated variant annotations." (PMID 32486089, 2020). "Germline BRCA mutations appear only in 3–5% of unselected BC patients, while TNBC with BLP are closely related to BRCA1 mutations, and 80–90% of BRCA1-abnormalities expressing cancers exhibited these phenotypes." (PMID 33171872, 2020). "Approximately 30% of this hereditary cancer risk is explained by genetic variants in high-penetrance susceptibility genes such as BRCA1 or BRCA2." (PMID 33198123, 2020). "This phenomenon, known as synthetic lethality, is exhibited by cancers with biallelic mutations in HR genes such as BRCA1 or BRCA2." (PMID 33002095, 2020). "The BRCA1 mutation is not only a cancer susceptibility gene in individuals with CRC or early onset CRC, but it also has great prognostic significance." (PMID 33193642, 2020). "TCGA database revealed that NSD2 and BRCA1 had a number of common mutations in different types of cancers and they have been accumulated in cancer cell." (PMID 32826945, 2020). "Overall, in the three datasets, a concordance-rate of 99.98% was detected in the interpretation of pathogenicity with one discordant variant BRCA1 p.L1365V (rs1567788936) in the German Cancer Consortium dataset." (PMID 32486089, 2020). "Cancers with BRCA1 or BRCA2 mutations exhibit substantial numbers of rearrangement signature 5 deletions." (PMID 33324554, 2020). "PARP1 inhibitors are expected to serve as therapeutic agents for various cancers such as breast cancer susceptibility gene 1 (BRCA1)- and BRCA2-associated hereditary breast and ovarian cancers, prostate cancer, non-small cell lung cancer, and Ewing sarcoma." (PMID 32405340, 2020). "When a germline mutation in BRCA1 or BRCA2 is detected in a cancer patient, genetic testing is indicated in all family members due to the increased risk associated with these mutations." (PMID 32545454, 2020). "In this work we aimed to identify selective cytotoxic compounds that target BRCA1-deficient cancer cells by Synthetic Lethality (SL) induction." (PMID 33424604, 2020). "Our work also highlights the importance of OXPHOS inhibitors, such as metformin, in treating BRCA1/2‐mutated cancers and other types of tumors affected by HR defects." (PMID 32400970, 2020). "Prior studies have also observed an association between POLQ overexpression in cancer with BRCA1/BRCA2 mutation and an over-representation of TMEJ-associated genomic scars." (PMID 33385162, 2020). "In the current study, we report on frequency and predictors of cancer-related distress in a large international cohort of unaffected women with BRCA1 or BRCA2 mutations aged 25 to 55 years." (PMID 32393849, 2020). "Based on the discovery of this synthetic lethality between BRCA and PARP, numerous PARPi have been developed, including olaparib, rucaparib, niraparib, talazoparib, and veliparib, which are mainly applied in cancer patients with BRCA1/2 mutations." (PMID 32526888, 2020).
cancer (continued). "Other mutational signatures including SBS40, SBS5, ID9, ID1 and ID2 were also enriched in BRCA1/2-mutated cancers expressing high levels of wild-type POLQ." (PMID 32885167, 2020). "One illustration of this is the sensitization of BRCA1- or BRCA2-deficient cancers to PARP inhibitors." (PMID 32660124, 2020). "Cancers cells with BRCA1/2 mutations are extremely sensitive to chemotherapy drugs such as platinum, that induce DNA double-strand breaks." (PMID 32950050, 2020). "Women with deleterious mutations in BRCA1/2 often spend a large part of their life dealing with their genetic risk of cancer." (PMID 33322597, 2020). "This study presents a guideline for BRCA-associated cancer-targeted therapy by analysing correlations between BRCA1/2 and different BC subtypes." (PMID 32719318, 2020). "Surprisingly, overexpression of these genes is mainly associated with the phenotype of HRR deficiency found in BRCA1/2 mutant cancer cells." (PMID 32719412, 2020). "Possible increases in cancer risk associated with fertility treatments in BRCA1/2 mutation carriers cannot be excluded at this time." (PMID 32719921, 2020). "These basal-like cancers frequently show mutations of or loss of expression of the BRCA1 tumor suppressor gene." (PMID 33162807, 2020). "Progress in understanding the consequences of BRCA1 mutations on DNA repair pathways evolved from this concept and had a significant impact on the treatment of cancers associated with the BRCA1 mutation carrier state." (PMID 32120796, 2020). "As BRCA1/2 gene mutations have prognostic value in cancer patients, the findings can have a high impact for the development of G4-interacting compounds effective in clinical settings." (PMID 33137181, 2020). "It has been found that inhibition of PARP1 and deficiency of BRCA1/2 synergistically kill BRCA1/2-deficient breast and other cancer cells via inhibiting DNA repair." (PMID 33665167, 2020). "Patient characteristics, positive family history of BRCA1/2-associated cancer, and cancer characteristics (Gleason score, prostate specific antigen level at diagnosis, and clinical tumor stage) were analyzed." (PMID 33351846, 2020). "Patients harboring BRCA1/2 mutations exhibit a higher risk of developing ovarian, prostate, and other cancers." (PMID 33324554, 2020). "Distinct copy number signature (“BRCA1-like”) is also shared between cancers related to germline mutation in BRCA1 gene and sporadic cancers whose BRCA1 protein was inactivated through other mechanisms." (PMID 32164626, 2020). "The carriers of more than one pathogenic variant in different cancer predisposing genes, BRCA1 and BRCA2 as an example, has been described but reports are not common." (PMID 32726901, 2020). "In BRCA1/2 mutations or deficiency status, cells are more likely to develop additional genetic alterations and chromosomal instability and can lead to cancer." (PMID 32686903, 2020). "53BP1 is an enigmatic DNA damage response factor that gained prominence because it determines the efficacy of PARP1 inhibitory drugs (PARPi) in BRCA1-deficient cancers." (PMID 31896689, 2020). "For example, ATRis (VE-821, VE-822, or AZ20) overcome acquired and pre-existing PARPis resistance in multiple BRCA1-deficient cancer cell lines of distinct origins." (PMID 33167404, 2020). "Conversely, in the non-BRCA carrier group, six patients (11.11%, 6/54) harbored a total of six mutations in other cancer susceptibility genes beyond BRCA1/2." (PMID 33194720, 2020). "Recently, to potentiate the effect of RAD52 drugs and reduce resistance, a new strategy named “dual synthetic lethality” has been proposed with the idea to combine them with PARP inhibitors, in BRCA1-deficient cancer cells." (PMID 32932697, 2020).
cancer (continued). "Poly (ADP-ribose) polymerase (PARP) inhibitors are a therapeutic milestone exerting a synthetic lethal effect in the treatment of cancer involving BRCA1/2 mutation." (PMID 33324554, 2020). "Of note, loss of PRIMPOL in BRCA1-deficient cancer cells significantly affects cell growth and viability, even in the absence of exogenous damage, underscoring the relevance of the PRIMPOL pathway for BRCA1-deficient cell survival." (PMID 31676232, 2020). "The current study provides further evidence that risk-reducing surgery is beneficial in reducing cancer-related distress in women with a BRCA1 or BRCA2 mutation." (PMID 32393849, 2020). "‘BRCAness’ is defined by the phenotypic similarities that some sporadic cancers share with those occurring in either BRCA1- or BRCA2-mutation carriers." (PMID 32235500, 2020). "Targeting BRCA1/2-deficient cancers using PARP inhibitors has been the archetype of synthetic lethality based on the inhibition of DNA damage repair (DDR) pathway." (PMID 32070411, 2020). "HR-deficient cancer cells with mutations in BRCA1 or BRCA2 are associated with DSB repair via error-prone repair pathways, the accumulation of mutations, and cell death." (PMID 33352723, 2020). "Of the cancer predisposition genes identified to date, BRCA1 and BRCA2 have been determined to be associated with hereditary breast and ovarian cancer syndrome." (PMID 32269964, 2020). "Tumors from these mice should reflect the characteristics of human cancers with complete loss of BRCA1 expression." (PMID 32257107, 2020). "Based on this synthetic lethality theory, PARP inhibitors (PARPis) were developed that increased the sensitivity of the synthetic lethal effect in cancer cells harboring BRCA1/2 mutations." (PMID 33324554, 2020). "By including family histories of any BRCA1/2-associated cancer, the FCH population of our study almost doubled compared to that of PC only." (PMID 33351846, 2020). "Taken together, these findings seem to forecast a potentially enhanced susceptibility of BRCA1/2-mutated HGSOCs to PD-1/PD-L1 inhibitors with respect to HR-proficient cancers." (PMID 32455819, 2020). "Here, we develop a genome-wide mutational scar-based pan-cancer Classifier of HOmologous Recombination Deficiency (CHORD) that can discriminate BRCA1- and BRCA2-subtypes." (PMID 33149131, 2020). "We evaluated how these PRS associations vary with age, cancer family history, and BRCA1/2 gene variant characteristics." (PMID 32665703, 2020). "Here, the authors analyze SNVs and CNVs simultaneously in bulk and single cells of BRCA1-associated breast tissues and cancers and show that Plekha5 deficiency promotes metastasis." (PMID 32978388, 2020). "BRCA1/2 is therefore a vital biomarker for the evaluation of the risk of OV and other related cancers, and also serves as a biomarker for personalizing treatment." (PMID 32950050, 2020). "Our analysis also revealed a mutation rate of 5.72% (30/524) in other cancer predisposition genes beyond BRCA1/2." (PMID 32091409, 2020). "Over 858 BRCA1 mutations have been confirmed to have a significant clinical impact on cancer susceptibility." (PMID 33013205, 2020). "Although BRCA1 mutation is commonly associated with cancer susceptibility, BRCA1 appears also as a key player in physiological situations." (PMID 32842712, 2020). "PARP inhibitors (PARPi) impair SSB repair, thereby causing DSBs that cannot be repaired efficiently in BRCA1/2-mutant cancers, leading to synthetic lethality." (PMID 33352723, 2020). "SBS3, ID6 and ID8 were enriched more in BRCA1/2-mutated cancers expressing high levels of wild-type POLQ than in other conditions." (PMID 32885167, 2020).
cancer (continued). "Recently, PARP inhibitors have been investigated not only as chemo/radiotherapy sensitizers, but also as single agents to selectively kill cancers defective in DNA repair, specifically cancers with mutations in BRCA1/2 genes." (PMID 33019612, 2020). "Family members of patients with FA who are heterozygous carriers of PV in genes from the fourth module FANCD1 (BRCA2), FANCJ (BRIP1), FANCN (PALB2), FANCO (RAD51C) and FANCS (BRCA1) are at increased risk to develop cancer." (PMID 33371494, 2020). "Together with a role in protecting replication forks, the requirement for BRCA1 in HDR is thought to underlie the etiology of BRCA1-deficient cancers." (PMID 31896689, 2020). "A 49-year-old unaffected female (BRCA2 PV/LPV carrier) with a strong family history of BRCA1/2-associated cancers lamented that it took almost nine years of “actively searching” before a doctor told her of the availability of genetic testing." (PMID 33110458, 2020). "Regardless, these data demonstrate that these mutations can activate multiple oncogenic pathways to overcome the lethal block of Brca1 deficiency in mammary epithelial cells to promote the initiation and progression of cancer formation." (PMID 32591500, 2020). "We also identified an example for overlooked exons represented by the breast cancer type 1 susceptibility protein (BRCA1)." (PMID 32591346, 2020). "In this study, we used the largest sample of women with pathogenic BRCA1/2 variants currently available to assess the associations between the most recently developed PRS with cancer risks for BRCA1/2 carriers." (PMID 32665703, 2020). "To identify candidates with high potential for BRCA1/2 mutations, we performed further analyses by modifying the original hereditary risk factors for PC into a novel risk factor for BRCA1/2-associated cancer." (PMID 33351846, 2020). "PARPi were particularly effective in the treatment of patients with breast, ovarian, or other cancers, who were BRCA1 and/or BRCA2 deficient." (PMID 32300589, 2020). "As BARD1 variants have also been identified in carriers of known cancer predisposing genes, BRCA1 and BRCA2, it will be important to explore if BARD1 variants modify risk in an epistatic or additive manner in this context." (PMID 32726901, 2020). "Several cancer-associated BRCA1 RING domain variants abolish binding to BARD1 and the E3 ubiquitin ligase activity." (PMID 32722046, 2020). "It is therefore possible that the BRCA1 deficiency not only causes cancer, but also facilitates the progression of EOAD and leads to earlier EOAD death." (PMID 32224926, 2020). "Methylation was positive in 82.6% (n=19/23) of the sporadic cancer samples that had loss of BRCA1 expression and 50% (n=2/4) of the samples with equivocal protein expression." (PMID 32856871, 2020). "All 139 probands were genetically tested for germline PVs in different cancer susceptibility genes, including BRCA1 and BRCA2, by NGS-based multi-gene panel testing." (PMID 32854451, 2020). "The association between FCH and PC severity remains controversial, for PC as well as other BRCA1/2-associated cancers." (PMID 33351846, 2020). "Lifetime risk, estimated frequency, types (such as ovarian, prostate, pancreatic and others) and characteristics (such as estrogen‐receptor expression) of cancers also vary between individuals with BRCA1 and BRCA2 mutations." (PMID 32638521, 2020). "Talazoparib has been FDA-approved for its efficacy against cancers with germline BRCA1 or BRCA2 mutations and HER2-negative metastatic breast cancer." (PMID 32046300, 2020). "Despite the clinical benefits of PARPi, most patients with disseminated BRCA1/2-mutated cancer still die because their tumors either show upfront resistance or develop secondary resistance." (PMID 32432041, 2020).
cancer (continued). "The knowledge came from observations in cancer cells deficient for BRCA1/2 genes, critical players of HRR, as G4 binders were shown to be more active in DSB accumulation and persistent checkpoint activation in these cell types." (PMID 33137181, 2020). "PARP inhibitors are currently used in the treatment of tumors displaying homologous recombination deficiencies such as breast and ovarian BRCA1/2-mutant cancers." (PMID 33333852, 2020). "Supporting the observations in human patients, most Brca1 knockout and mutations accelerate tissue-specific cancer development in mice." (PMID 32257107, 2020). "Considering that microtubule-associated tumor suppressors (such as breast cancer 1, BRCA1) can have major impact on cancer aggressiveness and clinical outcome, microtubule rearrangement through s-μg can indeed be a tool to influence the latter." (PMID 33027908, 2020). "Development of a PARP inhibitor has shed light on a synthetic lethal strategy to kill cancer cells in which BRCA1 dysfunction causes HR deficiency." (PMID 33231937, 2020). "In fact, it was under this paradigm that Olaparib (OLA, Lynparza, AZD-2281) reached U.S. Food and Drug Administration (FDA) approval to treat BRCA-1 mutated cancers (ucm572143, ucm592357, and NCT02987543)." (PMID 33167404, 2020). "Previous studies have shown that a family history of PC and BC is associated with PC risk; however, the association between BRCA1/2-related family cancer history (FCH) and PC aggressiveness remains controversial." (PMID 33351846, 2020). "Biallelic inactivation due to somatic alteration on top of a germline PTV was observed in 4.5% of patients overall, with 81% of these affecting known cancer-predisposition genes (such as BRCA1, BRCA2 and ATM)." (PMID 32025007, 2020). "PARPi have achieved great success in preclinical mouse models as well as in clinical trials to treat BRCA1-deficient cancers." (PMID 32257107, 2020). "Of interests, five out of the 10 BRCA1/2 germline variants harboring cases were observed in complex carcinomas suggestive of tissue type-specific mutations along with AKT1 somatic mutations." (PMID 32680987, 2020). "We used next generation sequencing (NGS) to investigate the possibility of other (somatic and/or germline) gene variants driving the cancer phenotype and the possibility of BRCA1/2 epigenetic silencing in the context of familial cancer predisposition." (PMID 31346352, 2019). "Inhibition of PARP-1 accelerates the damage of injured DNA, which especially leads to synthetic lethality in DNA-repairing-deficient cancer cells, for example BRCA1/2-deficient cells." (PMID 30427217, 2019). "Despite well-defined strategies for screening among individuals who are at increased risk for BRCA1/2-related cancers, cancer genetic services remain underutilized in clinical settings." (PMID 31083288, 2019). "Given the role of cancer predisposition factors such as BRCA1/BRCA2 and FA pathway in mitigating R-loops, it is reasonable that persistent R-loops are major contributing factors to cancer-associated genomic instability." (PMID 30813363, 2019). "Ubiquitin modification of H2A at K118/K119 is associated with transcriptional repression, and de-repression of satellite DNA has been reported in human and mouse BRCA1-deficient cancers." (PMID 31552267, 2019). "Among BC patients unselected for family cancer history, the prevalence of BRCA1 pathogenic variants varies from 0.5% to 3.1% in whites from the U.S., UK and Australia." (PMID 31013702, 2019). "BRCA1 mutation carriers and BRCA1/2 mutation carriers also showed significant association with family history of cancer, when compared with non‐BRCA mutation carriers (p = 0.049 and 0.014, respectively)." (PMID 30972954, 2019).